RNU6-751P (RNA, U6 small nuclear 751, pseudogene)
Gene: Small nuclear RNA gene on chromosome 19 (53,749,851 to 53,749,951, reverse strand). Ensembl gene ENSG00000252191.
Homologues: Orthologues: guinea pig U6 (75% identical). Paralogues in human: RNU6-1041P (83% identical), RNU6-982P (81% identical), RNU6-435P (80% identical), RNU6-803P (80% identical), RNU6-38P (79% identical), RNU6-1145P (78% identical), RNU6-1175P (78% identical), RNU6-1316P (78% identical), RNU6-165P (78% identical), RNU6-20P (78% identical), RNU6-28P (78% identical), RNU6-774P (78% identical), and 1286 more.